TLR4 (toll like receptor 4)
Diseases named in the same sentence as TLR4 in open-access papers (continued):
Sharing a sentence is not in itself a finding about the gene and the disease.
Hyperglycemia (continued). "Although antibiotic therapy significantly decreased blood glucose levels in diabetic mice, this small reduction in glycemia does not seem to reduce adrenal corticosterone production in diabetic mice, since neither TLR4 mutation nor treatment with TAK-242 interfered with hyperglycemia." (PMID 40496562, 2025). "Ten weeks after the onset of hyperglycemia, myenteric whole-mount preparations from the duodenum, ileum and colon of streptozotocin-induced diabetic, insulin-treated diabetic and control rats were prepared for TLR4/peripherin double-labelling fluorescent immunohistochemistry." (PMID 36672637, 2023). "Thus, the novel interaction between TLR4 rs11536889 and MyD88 rs7744 was related with an increased risk of CAD, that could be strengthened by the presence of hyperglycemia or hyperlipidemia." (PMID 26959040, 2016). "We investigated SNP–SNP interactions between the TLR4 and MyD88 genes in CAD susceptibility and assessed whether the effects of such interactions were modified by confounding risk factors (hyperglycemia, hyperlipidemia and Helicobacter pylori (H. pylori) infection)." (PMID 26959040, 2016). "It has been reported that hyperglycemia stimulates NADPH oxidase in the PKC pathway, thereby inducing TLR-2 and TLR-4 expression through PKC-α and PKC-δ, respectively." (PMID 39947694, 2025). "However, persistent activation of TLR4 signaling under chronic hyperglycemia might lead to dysregulated SG dynamics, either through premature disassembly or excessive inhibition, disturbing the delicate balance of translation control necessary for tendon homeostasis." (PMID 40855901, 2025). "Hyperglycemia of retinal ganglion cells increases the expression of TLR2 and TLR4, leading to the expression of proinflammatory molecules localized in the retinal area." (PMID 40076851, 2025). "For example, in condition of hyperglycemia, EVs derived from platelet-rich plasma (PRP) can induce retinal endothelial injury by transferring CXCL10 and upregulating the TLR4 signaling pathway." (PMID 38389842, 2024). "Since the authors previously showed that the Hsp70 on the surface of these exosomes is able to induce toll-like receptor 4 (Tlr4), leading to cardioprotective effects, they aimed to understand whether the Hsp70 present on the exosomal surface could be inhibited by the presence of hyperglycemia." (PMID 37509546, 2023). "HMGB1 is synthesized and secreted by immune cells, and in response to hyperglycemia or other stressors, HMGB1 binds TLR4 and RAGE." (PMID 37065747, 2023). "Molecular pathways such as the inhibition of NF-κB phosphorylation and NF-κB nuclear translocation, upregulation of TGF-β, TLR-4, TNF-α, ZO-1, GLP-2, and TGF-β1 by phytoconstituents can reduce AGEs and hyperglycemia-related complications." (PMID 37108833, 2023). "The inhibition of TLR4 expression improves bone metabolism, promotes ALP and bone mineralization, and reduces hyperglycemia-induced osteoblast apoptosis, levels of inflammatory factors, and the expression of Beclin 1 and LC3II/LC-I." (PMID 33995003, 2021). "In macrovascular cells, hyperglycemia induced activation of TLR2 and TLR4 through NOX-mediated ROS production." (PMID 34299310, 2021). "Previous studies have demonstrated that hyperglycemia activates the innate immune response mediated by TLR2, TLR4, and the NLRP3 inflammasome, inducing the production of various proinflammatory cytokines, including IL-1β, IL18, IL-6, and TNFα." (PMID 34356130, 2021). "Hyperglycemia and ROS production also promote TLR-2 and TLR-4 activation, with release of TNF-α, IL-1β, IL-8, monocyte chemoattractant protein (MCP-1), vascular cell adhesion molecule 1 (VCAM-1), intracellular adhesion molecule 1 (ICAM-1)." (PMID 31835864, 2019). "Our findings in an STZ-induced diabetic rat model confirm that hyperglycemia exacerbates RI/RI in terms of tubular damage and increased BUN and SCr concentrations via aggravation of oxidative stress, TLR4/NF-κB-mediated inflammation, and apoptosis." (PMID 31441362, 2019).
Hyperglycemia (continued). "The present study shows that intermittent hyperglycemia results in higher A-FABP expression and in an increased release of proinflammatory cytokines through TLR4-JNK pathways." (PMID 29850615, 2018). "Our aim of this study is to explore the function of the TLR4/NF-κB pathway in mitochondria-related oxidative damage and apoptosis of RTEC in hyperglycemia and to investigate the role of PGC-1α in the TLR4/NF-κB pathway in DKD." (PMID 29861832, 2018). "Our results suggest that miR-146a decreases the levels of hyperglycemia-induced TNFα possibly through the inhibition of HMGB1, TLR4, MyD88, and TRIF/IRF3 signaling." (PMID 26997759, 2016). "Activation of NF-κB is induced in hyperglycemia in REC, which can be induced by increased TLR4 levels under high glucose conditions." (PMID 26997759, 2016). "The plasma markers of this phenotype included: hyperglycemia, dyslipidemia and elevated plasma levels of ALT, leptin, TNFα and TLR2 and TLR4 activators." (PMID 26761430, 2016). "We found an that enhanced expression of the TLR4-MyD88-NF-kB pathway occurs in GDM placentae, which positively correlates with heightened local IR in placentae and higher maternal hyperglycemia." (PMID 27340831, 2016). "Therefore, we hypothesized that TLR4 and MyD88 were highly likely to be associated with hyperglycemia and hyperlipidemia, consistent with the effect-modification by hyperglycemia and hyperlipidemia that was observed in TLR4 rs11536889 and MyD88 rs7744 interaction." (PMID 26959040, 2016). "Hyperglycemia has been shown to upregulate TLR2, TLR4, MyD88, and IRAK-1 phosphorylation and TLR-mediated transactivation of NF-κB in human monocytes from T2DM patients." (PMID 24744784, 2014). "Strikingly, regain of TLR4 in myocytes of the Cre-recombinase injected leg in ID;Tlr4Myo;r-mS100A9 mice failed to improve hyperglycemia and increase glucose uptake indicating that myocyte TLR4 is dispensable for S100A9's glucoregulatory effects." (PMID 40874857, 2025). "In GDM, hyperglycemia induces HMGB1 release from placental trophoblasts, which activates Toll-like receptor 4 (TLR4) signaling, leading to increased production of inflammatory cytokines (including IL-8), impaired trophoblast migration, and a proinflammatory placental environment." (PMID 41020807, 2025). "Quantification confirms that hyperglycemia does not induce a significant change in TLR4 protein levels." (PMID 40855901, 2025). "In conclusion, this study demonstrates that hyperglycemia induces significant histological and molecular alterations in rotator cuff tendons, characterized by degenerative cellular changes and a pronounced upregulation of EGR1, TLR4, and NFκB transcripts." (PMID 40855901, 2025). "In patients with type 2 diabetes, hyperglycemia upregulates TLR2 and TLR4 expression in monocytes." (PMID 40429692, 2025). "Despite these insights, the impact of hyperglycemia on the expression of EGR1, TLR4, and NF-κB in rotator cuff tendons remains unclear." (PMID 40855901, 2025). "In the present study, we demonstrated that the hyperglycemia-triggered ATF6–CHOP axis aggravated IR-induced liver injury via inactivation of β-catenin, which in turn promoted TLR4-driven inflammatory responses, while simultaneously repressing Akt signaling molecules in the ischemic liver." (PMID 35289326, 2022). "Hyperglycaemia induced MMP-9 is inhibited by the administration of paeoniflorin via induction of SOCS3 (negative regulator of TLR signalling cascade), leading to inhibition of TLR4 signalling." (PMID 38983565, 2022). "Furthermore, the same alkaloids diminished hyperglycemia and hyperinsulinemia induced inflammation in HepG2 cells through the regulation of the NF- κB/JNK/TLR4 axis and the inhibition of downstream proinflammatory cytokines recruitment." (PMID 35327652, 2022).
Hyperglycemia (continued). "In keratinocytes, hyperglycemia dose-dependently up-regulates the expression of TNF-α to reduce the expression of Thrombomodulin (TM) and TLR4, exogenous supplementation of Recombinant sTM can increase the expression of TLR4 and promote DW healing." (PMID 33967796, 2021). "Likewise, DT administration led to a similar level of hyperglycemia in RIP-DTR; Tlr4−/− and RIP-DTR; Rage−/− mice and their littermate controls with intact TLR4 and RAGE, respectively, and S100A9 overexpression did not affect this parameter." (PMID 31391467, 2019). "However, using the in vitro model of hyperglycemia at 30 mM glucose, we found that cytokine production was diminished after TLR-2 and TLR-4 activation and that the intracellular growth of M. tuberculosis in human monocytes was not controlled." (PMID 31815150, 2019). "In adipocytes and in early stages of T2DM, Nox4 activity may be stimulated by hyperglycemia via an increased flow through the pentose phosphate shuttle and augmented NADPH, and by palmitate via a TLR4-dependent mechanism." (PMID 30265686, 2018). "Taken together, our data suggests hyperglycemia in diabetic mice may first up-regulate NADPH oxidase, which subsequently increases ROS products which are recognized as harmful by TLR4." (PMID 21159162, 2010). "Studies have also shown that TLR4 is increased in diabetic mice, however, the role of TLR4 in hyperglycemia-induced myocardial apoptosis has not been elucidated." (PMID 21159162, 2010). "Although the role of MD2 in hyperglycemia-induced cardiac inflammatory injury is unknown, these evidences point to the intriguing possibility that glucose or glucose-derived factors interact with MD2 to activate TLR4." (PMID 32358497, 2020). "However, the role of TLR4 in enhancing apoptosis of cardiomyocytes induced by hyperglycemia has not been characterized." (PMID 21159162, 2010). "In addition, miR-27a downregulates Toll-like receptor 4 (TLR4) expression in human RPECs when exposed to high glucose, suggesting a miR-27a protective role in inhibiting RPEC inflammation and apoptosis during hyperglycemia-mediated diabetic retinopathy pathogenesis." (PMID 37566749, 2023). "Increased TLR4 expression in various tissues and LDL oxidation in the circulation proceed simultaneously under diabetic conditions; nevertheless, previous studies have investigated the effects of increased TLR4 or oxLDL alone but the combined effects of hyperglycaemia have not been examined." (PMID 38525707, 2024).
autoimmune disease (119 papers, 2009 to 2025). A disorder resulting from loss of function or tissue destruction of an organ or multiple organs, arising from humoral or cellular immune responses of the individual to their own tissue constituents. "The pro‐inflammatory activity of TLR4 is also implicated in pathological responses to endogenous ligands under chronic inflammatory conditions, such as autoimmune diseases, ankylosing spondylitis (AS), and neurodegenerative diseases." (PMID 39508636, 2024). "The activation of the TLR4 pathway is the main pathway by which PT causes autoimmune diseases as an adjuvant." (PMID 39596635, 2024). "IRF3 and IRF7, which are associated with MyD88-independent pathway of TLR4 signalling, also play crucial roles in development of autoimmune disease or CRSwNP, and these molecules are thought to act as pro-inflammatory transcription factors in these diseases." (PMID 35256715, 2022). "Prolonged activation of TLR4 is also linked with several human hereditary and neurodegenerative diseases and also with autoimmune diseases and cancer." (PMID 33057840, 2021). "TLR4 is also associated with the development of allergies and some autoimmune diseases, like Crohn's disease, asthma, and type 1 diabetes." (PMID 33057840, 2021). "TLR4 is a receptor for LPS, and the pro-inflammatory activity of TLR4 is linked with pathological responses to endogenous ligands in autoimmune disorders." (PMID 31889967, 2019). "Inappropriate activation of TLRs, such as TLR4, and downstream pathways have been implicated in certain autoimmune diseases, including MS." (PMID 31561751, 2019). "In the current study, 1074 RA, 217 JIA and 2070 healthy controls were genotyped for six polymorphisms in the TLR4 gene that was previously reported to be associated with autoimmune diseases." (PMID 28222760, 2017). "Some researchers have reported that TLR4 rs11536889 polymorphism is associated with a variety of autoimmune diseases, such as Grave’s disease and autoimmune pancreatitis." (PMID 26959040, 2016). "Through DAMP recognition, TLR4 is implicated in a diverse range of pathologies, including autoimmune diseases, inflammatory disorders, thrombosis, and cancer." (PMID 27775020, 2016). "TLR4 signalling up-regulates IL-6, and aberrant expression of both of these genes has been implicated in some autoimmune diseases." (PMID 24944008, 2015). "TLR4 was also found to be associated with the response to rituximab, which is used in the treatment of many lymphomas, leukemias, and some autoimmune disorders." (PMID 20419126, 2010). "Exposure to infectious agents that stimulate TLR4 signaling is known to modulate the risk of autoimmune disease in humans and is critical to some animal models of autoimmunity." (PMID 20049214, 2009). "Excessive TLR4 activation has been associated with chronic inflammation and autoimmune diseases." (PMID 38140398, 2023). "In particular, TLR4 reportedly recognizes not only PAMPs but also endogenous DAMPs such as high mobility group box 1 protein, which are released when host cells are damaged, and is associated with inflammatory and autoimmune diseases." (PMID 36416450, 2023). "Polymorphisms of TLR4 have been associated with autoimmune diseases in the skin or elsewhere." (PMID 34468896, 2021). "Notably, prolonged activation of TLR4 is linked with several hereditary human diseases, neurodegeneration and also with autoimmune diseases and cancer." (PMID 33057840, 2021). "Interestingly though, the enriched target genes showed co-expression in the mature CD19+ B cell subset and some of them (IL-6, IL-13, PRDM1 and TLR4) have been reported to be associated genetically with autoimmune diseases." (PMID 33897713, 2021). "Excessive or inappropriate TLR4 activation causes the development of many autoimmune diseases." (PMID 33597886, 2020). "Autoimmune diseases that have been associated with TLR4 include RA, SLE and type 1 diabetes." (PMID 33243158, 2020).
autoimmune disease (continued). "Our data suggest that the interplay between IL-1Ra, intestinal microbiota, TLR4, and mucosal T cells may serve as a potential predisposing or initiating event in the context of autoimmune disease and provide opportunities to control RA." (PMID 28645307, 2017). "Since TLR4 activation is associated with many inflammatory and autoimmune diseases, B. quintana LPS might be considered a new therapeutic strategy for TLR4-driven pathology." (PMID 27670746, 2016). "The authors hypothesized reduced TLR4 function as an explanation of increased infection associated with immunosuppressive therapy for autoimmune disease." (PMID 22937165, 2012). "In addition, in B-chronic lymphoblastic leukemia (B-CLL), the reduced TLR4 expression was associated with increased risk of disease progression and a poor outcome, infectious episodes, and evolution to autoimmune diseases, which suggests an impaired innate immunity." (PMID 36071076, 2022). "TAK-242, a small-molecule TLR4 inhibitor, is widely used to suppress TLR4/NF-κB pathway activation in studies of inflammation, cancer, and autoimmune diseases." (PMID 40640887, 2025). "The regulatory effect of HMGB1 on IL‐17A expression and function has been reported in some inflammatory and autoimmune diseases by the HMGB1‐Toll‐like receptor 4 (TLR4)‐interleukin (IL)‐23‐IL‐17A pathway." (PMID 38414294, 2024). "TLR4 signaling has been found to be an important pathway in the pathogenesis of many autoimmune diseases including myocarditis." (PMID 38550582, 2024). "Intrinsic TLR4 signal transduction in B cells plays an important role in autoimmune diseases, which differs from the role in the HMGB1/TLR4/NF-κB inflammatory signaling pathway." (PMID 37872565, 2023). "TLR4 is known for its roles in pathogen recognition and activation of innate immunity, but also for its involvement in autoimmune disorders such as multiple sclerosis." (PMID 35806122, 2022). "IL-33/ST2 signaling has been found to upregulate CD11b, TLR4, caspase-1, and IL-1β in a number of human and animal studies of infection and autoimmune disease." (PMID 36741845, 2022). "Recently, NI-0101, an anti-toll-like receptor 4 monoclonal antibody was used in RA, which was the first clinical trial to target TLRs to treat autoimmune diseases." (PMID 35126357, 2021). "Our results underscore the importance of phenotype conversion probably related to the TLR4 expression and activation, in the design of future clinical protocols to treat patients with inflammatory and autoimmune diseases." (PMID 32988406, 2020). "In a recent study, it has been found that LPS from Bacteroides dorei with TLR4 antagonist properties was abundant in children from countries with an early onset of autoimmune disease." (PMID 31906991, 2020). "Our findings identify a new drug candidate and therefore provide a possible novel therapeutic strategy through inhibiting TLR4 activity in patients with chronic inflammatory and autoimmune diseases." (PMID 32397494, 2020). "There is evidence of harmful microbiota-derived TLR4 antagonistic LPS effects on health promoting the development of autoimmune diseases." (PMID 31906991, 2020). "Our findings that TLR2 and TLR4 expression and induction are altered in children with DS suggest a possible role for these pathogen receptors in the development of autoimmune diseases in this group." (PMID 31611734, 2019). "Improper TLR4 activation in innate immune cells is correlated with many autoimmune diseases, including MS." (PMID 31561751, 2019). "In recent years, TIRAP has been investigated intensively because of its importance in the signal transduction pathway of TLR4—the principal agent responsible for sepsis, an endotoxin-induced deadly autoimmune disease." (PMID 29434596, 2018).